BCR (BCR activator of RhoGEF and GTPase)
Diseases named in the same sentence as BCR in open-access papers (continued):
Sharing a sentence is not in itself a finding about the gene and the disease.
chronic myeloid leukemia (continued). "The fifth edition of the WHO Classification has updated the name of atypical chronic myeloid leukemia, BCR::ABL1-negative (aCML), and replaced it with myelodysplastic syndrome/myeloproliferative neoplasms with neutrophilia (MDS/MPN with neutrophilia), while the ICC has kept the original name." (PMID 37370785, 2023). "Similarly, the ICC uses a 10% blast cutoff for most molecularly defined subtypes of AML, again with the exception of BCR::ABL1 to avoid confusion with the diagnosis of chronic myeloid leukemia (CML)." (PMID 36966300, 2023). "Hematologic malignancy studies use similar categorical response criteria to classify continuous assessments of disease burden, such as percent blasts in Acute Myeloid Leukemia (AML), BCRABL/BCR ratio in Chronic Myeloid Leukemia (CML), and M-protein in multiple myeloma (MM)." (PMID 36870005, 2023). "The achievement of major molecular response (MMR, BCR::ABL1 ≤ 0.1% IS) within the first year of treatment with tyrosine kinase inhibitors (TKI) is a milestone in the therapeutic management of patients with newly diagnosed chronic myeloid leukemia (CML)." (PMID 37174118, 2023). "S1g-2 and S1g-6 significantly inhibited the growth of chronic myeloid leukemia in vitro and in vivo, and more importantly, S1g-2 exhibited an ever-growing ability to induce apoptosis and increase BCR-ABL independent TKI resistance in chronic myeloid leukemia cells." (PMID 37189349, 2023). "Additionally, chronic myeloid leukemia patients with BCR-ABL chromosomal translocation displayed alternative splicing variants of BCR-ABL when treated with imatinib, the tyrosine kinase inhibitor." (PMID 36505780, 2022). "Chronic myeloid leukaemia (CML) is a haematological neoplasm driven by the BCR/ABL fusion oncogene." (PMID 35742831, 2022). "Cancer is influenced by several factors including the activation of proto-oncogenes through chromosomal translocations such as the presence of the Philadelphia chromosome, which is the result of the translocation of the BCR-ABL genes present in most patients with chronic myeloid leukemia (CML)." (PMID 36012357, 2022). "Gene mutations independent of BCR::ABL1 have been identified in newly diagnosed patients with chronic myeloid leukemia (CML) in chronic phase, whereby mutations in epigenetic modifier genes were most common." (PMID 35902731, 2022). "Remarkably, phosphatases can influence the response to TKI treatment as reported for PTPN1 (PTP1B), PTPN6 (SHP1) and PTPRC (CD45) for BCR-ABL TKIs treatment in chronic myeloid leukemia or for PTPN11 (SHP2) for acquired resistance to ALK-TKIs in ALK-rearranged non-small cell lung cancer (NSCLC)." (PMID 36698412, 2022). "In chronic myeloid leukemia, the ability of the leukemia stem cells to choose from the many fates that are available to normal hematopoietic stem cells appears to be deregulated by BCR-ABLp210 and changes to the epigenome are also important." (PMID 36362357, 2022). "Chronic Myeloid Leukemia (CML) is a myeloproliferative disease caused by a translocation between chromosomes 9 and 22 (called Philadelphia chromosome) resulting in the fusion of two genes, ABL1 (Ch9) and BCR (Ch22)." (PMID 36499332, 2022). "Chronic myeloid leukemia (CML) is a myeloid proliferative disorder driven by constitutive activation of tyrosine kinase due to abnormal chromosome translocation with the formation of BCR-ABL (breakpoint cluster region-Abelson) fusion gene." (PMID 35443725, 2022). "Similarly, in chronic myelogenous leukemia carrying BCR-ABL fusion, PI3K-mTORC1 signaling downstream of BCR-ABL receptor tyrosine kinase (RTK) activity increases ROS through elevated glycolysis and mitochondrial respiration." (PMID 36282248, 2022). "For example, in chronic myelogenous leukemia, the high tyrosine kinase activity of the chimeric BCR-ABL protein is derived from the fusion of the phosphorylation domain encoded by the BCR gene with the non-receptor tyrosine kinase domain encoded from the ABL proto-oncogene." (PMID 33980272, 2021).
chronic myeloid leukemia (continued). "An example would be imatinib mesylate (Gleevec, Novartis) that targets the Philadelphia chromosome (BCR-ABL fusion) protein in chronic myeloid leukemia (CML) patients, competitively binding to its Adenosine triphosphate (ATP) domain and disrupting the tyrosine kinase activity." (PMID 34309639, 2021). "The beginning of deciphering these mechanisms started with the identification of the pathogenetic role of the chimeric BCR/ABL oncogene in chronic myeloid leukemia (CML), which arises as a result of reciprocal t(9:22) translocation forming the so-called Philadelphia chromosome." (PMID 33921387, 2021). "To study if the selectivity profile of eCF506 translate into weaker phenotypic activity against ABL-driven cancer cells relative to classical SRC/ABL inhibitors, we performed cell proliferation assays with three BCR-ABL-positive chronic myeloid leukemia (CML) cell lines: LAMA-84, KCL-22, and K-562." (PMID 34417202, 2021). "ABL1 is a proto-oncogene encoding a nonreceptor tyrosine kinase, best known in the somatic BCR-ABL fusion gene associated with chronic myeloid leukaemia." (PMID 33223528, 2021). "Chronic myeloid leukemia (CML) is a hematological malignancy resulting from BCR-ABL fusion." (PMID 34425750, 2021). "In contrast to gene fusions involving protein kinases, such as the BCR-ABL fusion in chronic myeloid leukemia, therapeutic targets for cancers harboring gene fusion involving transcription factors are more elusive owed to their complex functions, as shown in this study." (PMID 33685520, 2021). "One well-characterized example is the BCR-ABL gene fusion in chronic myeloid leukemia (CML)." (PMID 35582389, 2021). "Because the Philadelphia chromosome (Ph+) resulting in the BCR-ABL fusion protein presents a unique disease cause and therapeutic target, chronic myeloid leukemia (CML) is set apart as the only member of Ph+ MPN in the World Health Organization (WHO) classification of MPN." (PMID 32806517, 2020). "PROTACs have already been applied for the degradation of various notable targets, including abelson murine leukemia viral oncogene homolog 1 (ABL)-breakpoint cluster region (BCR) in chronic myeloid leukemia, bromodomain proteins in multiple cancers, and androgen receptor in prostate cancer 53,71,72." (PMID 32944392, 2020). "As the first success of targeted medicine, imatinib significantly advanced therapeutic strategies for chronic myeloid leukemia (CML) through inhibiting the breakpoint cluster region-Abelson (BCR-ABL) fusion protein, which drives constitutive tyrosine kinase activity." (PMID 30836705, 2019). "Chronic myeloid leukemia (CML) arises following a reciprocal chromosomal translocation within a haematopoietic stem cell (HSC) leading to expression of the fusion oncoprotein BCR-ABL." (PMID 30185934, 2019). "In addition to chronic myeloid leukaemia (CML) characterized by the BCR-ABL fusion gene, the three most common myeloproliferative neoplasms are essential thrombocythemia (ET), polycythemia vera (PV), and primary myelofibrosis (PMF)." (PMID 28031530, 2017). "The BCR/ABL1 translocation often occurs in chronic myeloid leukemia (CML)." (PMID 28690958, 2017). "For instance, BCR-ABL fusions are characteristic of chronic myeloid leukemia." (PMID 28359308, 2017). "JAK2 inhibition can inactivate Lyn kinase in BCR/ABL-induced Chronic Myeloid Leukemia (CML)." (PMID 29029406, 2017). "The BCR-ABL fusion gene is the major oncogene in chronic myelogenous leukemia (CML)." (PMID 28086240, 2017).
chronic myeloid leukemia (continued). "Dasatanib has been used extensively as a second-line therapy in patients with chronic myelogenous leukemia with the BCR-ABL fusion protein, but, along with other c-Src-targeting TKIs, has produced generally disappointing results in solid malignancy clinical trials." (PMID 26918609, 2016). "The BCR-ABL fusion protein, generated following translocation of ABL to the BCR gene, leads to constitutive activation of the ABL tyrosine kinase in 95% of chronic myeloid leukemia and cells depend on BCR-ABL activity for the execution of the oncogenic program." (PMID 27732969, 2016). "The formation of the BCR-ABL fusion sequences is dependent on the reciprocal translocation between chromosome 9 and 22, originating the Philadelphia chromosome (Ph + chromosome), which is the molecular hallmark of chronic myeloid leukemia (CML)." (PMID 27185032, 2016). "Imatinib (Gleevec, Novartis, Basel, Switzerland) revolutionized therapeutic strategies for chronic myeloid leukemia (CML) through targeting the BCR-ABL fusion protein, which drives constitutive tyrosine kinase activity and in turn the malignant behaviors of leukemic cells." (PMID 26370727, 2015). "Based on reports of over-expression of EphA2 in human leukemia and our own analysis of clinical samples, we examined expression of EphA2 gene in two models of leukemia, the MLL-AF9 model of acute myeloid leukemia and the BCR-ABL model of chronic myeloid leukemia." (PMID 26083390, 2015). "Finally, the PERK-eIF2α axis is robustly elevated in chronic myeloid leukemia (CML) cells that also express high levels of BCR-ABL." (PMID 26622781, 2015). "Consistent with this possibility is the recent finding that a microRNA (miR-203) that targets and suppresses expression of the BCR-ABL fusion protein is hypermethylated in several hematopoietic tumors including chronic myelogenous leukemias and some lymphoblastic leukemias." (PMID 26177635, 2015). "Recent data shows that the combination therapy of TG-101348 and BI-2536 (PLK1 inhibitors) synergistically targets oncogenic pathways and that the combination therapy of TG101348 and imatinib (ABL kinase inhibitor) inhibits cell proliferation of BCR-ABL-positive chronic myeloid leukemia cells." (PMID 25869210, 2015). "The canonical example, of course, is the use of imatinib in the treatment of chronic myelogenous leukemia harboring the BCR/ABL rearrangement.A more recent example is the remarkable success of BRAF inhibitors in the treatment of malignant melanomas with BRAF V600E mutations." (PMID 25286031, 2014). "Secondly, it is well known that chronic myeloid leukaemia (CML) is a disease guided via a molecular defect on the BCR-ABL translocation, resulting in: activation and dysregulation of a large number of signalling pathways, including cell division changes and also genetic-abnormalities incorporation." (PMID 24912534, 2014). "Although some such cancer biomarkers have been identified (for example, translocation of parts of chromosomes 9 and 22 in chronic myelogenous leukemia, which creates an oncogenic BCR-ABL gene fusion; and some other translocations in rare cancers) these are the exceptions." (PMID 25220599, 2014). "Similar to AML, chronic myeloid leukemia cases with BCR-ABL translocations had unmethylated WT1 promoters and AWT1 hypermethylation, however, polycythaemia vera and essential thrombocythaemia samples had methylation profiles indistinguishable from normal leukocyte controls." (PMID 24405639, 2014). "For example, the BCR/ABL1-positive chronic myelogenous leukemia line K562 is resistant to JQ1; however, it may be sensitive to triptolide because triptolide may have a more penetrant effect on global transcription than JQ1." (PMID 24576043, 2014). "Chronic myeloid leukemia is caused by translocation of chromosomes 9 and 22 in a hematopoietic stem cell (HSC) resulting in the formation of the constitutively active tyrosine kinase BCR/ABL1 and the subsequent generation of an LSC." (PMID 24427158, 2013).
chronic myeloid leukemia (continued). "Chronic myeloid leukemia (CML) is an acquired myeloproliferative disorder that originates in an abnormal pluripotent bone marrow stem cell and is consistently associated with the presence of the Philadelphia (Ph) chromosome, usually leading to a BCR-ABL gene fusion." (PMID 23761821, 2013). "The BCR/ABL fusion tyrosine kinase is expressed in chronic myeloid leukemia and Philadelphia-positive (Ph+) acute lymphoblastic leukemia cells, and its inhibition by the clinically used tyrosine kinase inhibitors imatinib or dasatinib induces apoptosis of these cells." (PMID 23233201, 2013). "Interestingly, JAK2 has been identified to be involved in two rare translocations: with ETV6, at 12p13, in acute lymphoblastic leukemia and rarely myeloproliferative (CML-like) disorder and with BCR, at 22q11.2, in patients with chronic myeloid leukemia." (PMID 22549126, 2012). "The Philadelphia chromosome, resulting from a reciprocal translocation between chromosomes 9q34 and 22q11, generates a 190- or 210-kDa fusion protein BCR-ABL identified in more than 95% of chronic myeloid leukemia (CML) and half of patients with adult-onset acute lymphoblastic leukemia (ALL)." (PMID 21647292, 2011). "Chronic myeloid leukemia (CML) is initiated from the BCR-ABL-expressing leukemia stem cells (LSCs)." (PMID 21297225, 2010). "Since Gleevec (imatinib mesylate, STI571) was approved by the FDA as first-line treatment for chronic myeloid leukemia with the oncoprotein BCR-ABL expression in 2001, molecular targeted therapy for various cancers has become an area of intense basic science and clinical research." (PMID 19390592, 2009). "The aim of this study was to map the transcriptional response of cells to the activity of the fusion oncogene BCR/ABL1, associated with chronic myeloid leukemia (CML), in a reverse way by blocking the activity of the fusion protein using the tyrosine-kinase inhibitory drug imatinib mesylate." (PMID 17488501, 2007). "For example, blockade of signaling molecules within the Ras/MEK or PI3K/mTOR pathways might augment the effects of EGFR therapeutics, similar to their effects on chronic myelogenous leukemia cells when used in conjunction with the BCR-ABL inhibitor imatinib." (PMID 17973573, 2007). "Here, we demonstrate that inhibition of the oncogenic kinase BCR::ABL1 in chronic myeloid leukemia (CML) cells induces ribosome collisions and activates the ribotoxic stress response (RSR)." (PMID 41912913, 2026). "We demonstrate the utility of this methodology in the context of chronic myeloid leukemia (CML), where longitudinal monitoring of BCR::ABL1 transcript levels guides treatment decisions." (PMID 41542066, 2026). "In chronic myeloid leukemia (CML), the discovery of the BCR-ABL fusion gene established tyrosine kinase inhibitors as the standard of care." (PMID 41228293, 2025). "Tyrosine kinase inhibitors (TKIs) targeting BCR::ABL1 have greatly improved the survival of patients with chronic myeloid leukemia (CML), and their teratogenicity appears as an important factor for individuals of childbearing potential." (PMID 40442861, 2025). "Chronic myeloid leukemia (CML) is a stem cell‐driven neoplasia characterized by the expression of the constitutively active tyrosine kinase (TK) BCR/Abl." (PMID 41128634, 2025). "Breakpoint Cluster Region-Abelson (BCR::ABL1) fusion protein is essential in the pathogenesis of chronic myeloid leukemia (CML); however, the chronic-to-blast phase transformation remains elusive." (PMID 41502514, 2025). "Chronic myeloid leukemia (CML) is a myeloproliferative neoplasm characterized by the presence of the Philadelphia chromosome and the BCR/ABL1 fusion gene." (PMID 41341402, 2025). "Chronic myeloid leukemia (CML) is initiated and maintained by BCR::ABL which is clinically targeted using tyrosine kinase inhibitors (TKIs)." (PMID 38307941, 2024).
chronic myeloid leukemia (continued). "Notably, BCR-ABL fusion gene testing ruled out chronic myeloid leukemia, and no other driver or non-driver gene mutations were detected." (PMID 39395952, 2024). "While BCR::ABL1 tyrosine kinase inhibitors have transformed the treatment paradigm for chronic myeloid leukemia (CML), disease progression and treatment resistance due to BCR::ABL1-dependent and BCR::ABL1-independent mechanisms remain a therapeutic challenge." (PMID 39063200, 2024). "However, it was also observed that microRNA 7-5p may have a relationship with chronic myeloid leukemia and the BCR::ABL1 transcript in different ways." (PMID 38542337, 2024). "A prominent, safe and efficient therapy for patients with chronic myeloid leukemia (CML) is inhibiting oncogenic protein BCR::ABL1 in a targeted manner with imatinib, a tyrosine kinase inhibitor." (PMID 39182842, 2024). "Chronic myeloid leukemia (CML) is characterized by the presence of Philadelphia chromosome (Ph) containing the BCR::ABL1 fusion gene with e13a2 and e14a2 as the most frequent transcript types." (PMID 38337473, 2024). "Chronic myeloid leukemia (CML) is a type of leukemia whose main genetic marker is the reciprocal translocation that leads to the production of the BCR::ABL1 oncoprotein." (PMID 38542337, 2024). "Furthermore, in MLN with FGFR1 rearrangements, translocations involving ZMYM2 are more commonly associated with a T-lymphoblastic lymphoma phenotype, whereas translocations involving BCR tend to lead to a phenotype resembling BCR::ABL1 positive chronic myeloid leukemia." (PMID 37076693, 2023). "This fusion gene BCR::ABL1 was studied for years in Chronic Myeloid Leukemia (CML) and permitted to explain its physiopathology." (PMID 36980287, 2023). "Breakpoint cluster region-Abelson gene (BCR-ABL) tyrosine kinase inhibitors (TKIs) have revolutionized the treatment of patients with chronic myeloid leukemia (CML)." (PMID 36824461, 2023). "Hence, the suppression of the proliferation of BaF3-T315I cells by cell differentiation induced by I13 may be originated from the repression of the chronic myeloid leukemia signaling pathway via the modulation of BCR-ABL." (PMID 37124196, 2023). "Great progress in the treatment of patients with chronic myeloid leukemia has been made with the introduction of tyrosine kinase inhibitors (TKIs), which is the first targeted molecular therapy since it is a competitive inhibitor of the BCR::ABL tyrosine kinase protein." (PMID 37763683, 2023). "Chronic myeloid leukemia (CML) is a clonal expansion of the progenitor hematopoietic stem cells arising from the existence of the fusion BCR-ABL oncogene, that represents 15%-20% of the newly diagnosed cases of leukemia patients 1-2." (PMID 37215441, 2023). "Chronic myeloid leukemia (CML) is characterized by a massive expansion of predominately myeloid lineage cells driven by the constitutively active BCR::ABL1 fusion tyrosine kinase." (PMID 37932786, 2023). "The BCR-ABL fusion protein kinase is a unique oncogenic driver of chronic myeloid leukemia (CML) by affecting hematopoietic stem cells." (PMID 38068992, 2023). "Chronic myeloid leukemia (CML) is a myeloproliferative disorder that is effectively treated with tyrosine kinase inhibitors (TKIs), targeting the BCR::ABL1 fusion protein." (PMID 38012567, 2023). "Patients with chronic myeloid leukemia (CML) show resistance to tyrosine kinase inhibitors (TKIs) targeting ABL1 due to the emergence of BCR::ABL1 mutants, especially compound mutants during the treatment, which brings great challenges to clinical practice." (PMID 36263131, 2022). "The BCR-ABL fusion protein is the key factor that results in the occurrence of chronic myeloid leukemia (CML)." (PMID 36058922, 2022). "Diagnostic criteria of atypical chronic myeloid leukemia, BCR/ABL1 negative." (PMID 34868917, 2021). "Chronic myeloid leukemia (CML) is featured by the chromosomal translocation of 22q1 with 9q34 to produce a BCR/ABL1 fusion gene." (PMID 34781898, 2021).